ST6GAL2 (ST6 beta-galactoside alpha-2,6-sialyltransferase 2)
Description:
Transfers sialic acid from the donor of substrate CMP-sialic acid to galactose containing acceptor substrates. Has alpha-2,6-sialyltransferase activity toward oligosaccharides that have the Gal-beta-1,4-GlcNAc sequence at the non-reducing end of their carbohydrate groups, but it has weak or no activities toward glycoproteins and glycolipids.
Synonyms: ST6GalII; KIAA1877; SIAT2
Tractability: Antibody: UniProt predicts a signal peptide or a membrane-spanning region.
Gene: Protein-coding gene on chromosome 2 (106,801,600 to 106,887,284, reverse strand). Ensembl gene ENSG00000144057.
Subcellular location: Golgi apparatus, Golgi stack membrane
Subcellular location (Human Protein Atlas): Nucleoli fibrillar center; Nucleoplasm
Pathways (Reactome):
Metabolism of proteins: Sialic acid metabolism
Gene Ontology:
Molecular function: beta-galactoside alpha-2,6-sialyltransferase activity; sialyltransferase activity
Biological process: oligosaccharide metabolic process; sialylation; carbohydrate metabolic process; glycoprotein biosynthetic process
Cellular component: Golgi apparatus; Golgi membrane; Golgi cisterna membrane
Genetic constraint (gnomAD): Loss-of-function variants: 22 observed, 32.11 expected, observed/expected ratio (o/e) 0.69, 90% interval 0.49 to 0.98. The upper end of that interval is the gene's LOEUF score, 0.98, which puts it in group 4 of 6, group 1 being the genes least tolerant of losing a copy. Missense variants: 677 observed, 650.68 expected, observed/expected ratio (o/e) 1.04, 90% interval 0.98 to 1.11. Synonymous variants: 283 observed, 268.69 expected, observed/expected ratio (o/e) 1.05, 90% interval 0.95 to 1.16.
Homologues: Orthologues: chimpanzee ST6GAL2 (99% identical), macaque ST6GAL2 (97% identical), rabbit ST6GAL2 (86% identical), dog ST6GAL2 (81% identical), mouse St6gal2 (77% identical), rat St6gal2 (77% identical), pig ST6GAL2 (75% identical), guinea pig ST6GAL2 (67% identical), tropical clawed frog st6gal2 (60% identical), zebrafish st6gal2a (52% identical), zebrafish st6gal2b (43% identical). Paralogues in human: ST6GAL1 (31% identical), ST6GALNAC1 (15% identical), ST3GAL3 (15% identical), ST3GAL5 (15% identical), ST3GAL1 (15% identical), ST3GAL4 (14% identical), ST6GALNAC2 (13% identical), ST6GALNAC5 (13% identical), ST3GAL2 (12% identical), ST3GAL6 (12% identical), ST6GALNAC4 (12% identical), ST6GALNAC3 (11% identical), and 2 more.
Diseases named in the same sentence as ST6GAL2 in open-access papers:
ST6GAL2 is named in the same sentence as 21 diseases in open-access papers, as found by Europe PMC text mining. Sharing a sentence is not in itself a finding about the gene and the disease. The quoted sentences say what the papers report.
breast carcinoma (8 papers, 2020 to 2022). "In breast cancer ST6GAL2 expression associated with poor prognosis for patients." (PMID 34975914, 2021). "It was found that an increase in tumor infiltrating lymphocytes (TIL) was associated with low expression of ST6GAL1 in epidermal growth factor receptor 2-overexpressing (HER2) breast cancers and by high expression of ST6GAL2 in triple-negative breast cancers." (PMID 33921986, 2021). "While relatively few studies have investigated the expression and role of ST6GAL2 in tumors, overexpression of this enzyme was found in select types of cancer, including breast cancer and follicular thyroid carcinoma (FTC)." (PMID 34975914, 2021). "Moreover, silencing of ST6GAL2 in breast cancer cells resulted in reduced xenograft tumor growth in vivo." (PMID 34975914, 2021). "In contrast, a recent report pointed to a tumor promoting role of ST6GAL2 in breast cancer." (PMID 33921986, 2021). "Moreover, silencing ST6GAL2 in breast cancer cells reduced xenograft tumor growth in vivo." (PMID 36547200, 2022). "Similar to this, ST6GAL2 silencing reduced the proliferation of MCF-7 and T47D breast cancer cells by stopping cell cycle progression at the G0/G1 phase and decreasing the proportion of cells in the S phase." (PMID 36547200, 2022). "A recent report analyzed the relationship between the α-2,6 sialyltransferases ST6GAL1, ST6GAL2, and ST6GALNAC1 and tumor-infiltrating lymphocyte (TIL) in different breast cancer molecular subgroups." (PMID 33921986, 2021). "Similarly, ST6GAL2 silencing inhibited MCF-7 and T47D breast cancer cell proliferation by arresting cell cycle progression at G0/G1 phase and reducing the fraction of cells in S phase." (PMID 33921986, 2021).
follicular thyroid carcinoma (4 papers, 2019 to 2021). "Briefly elaborated as follows:In thyroid carcinoma, HCP5 promoted the proliferation, migration, invasiveness and angiogenic ability of follicular thyroid carcinoma cells via sponging miR-22-3p, miR-186-5p, miR-216a-5p and activating ST6GAL2." (PMID 34923990, 2021). "In follicular thyroid carcinoma, up-regulated ST6GAL2 in advanced cells and its co-expression with LncRNA HCP5 was strongly associated to cell proliferation, migration, invasiveness and angiogenesis." (PMID 30704472, 2019). "The long non-coding RNA–HLA complex P5 (HCP5) has been found to be overexpressed in follicular thyroid carcinoma and functions as a sponge for miR-22-3p, miR-186-5p and miR-216a-5p, which activates ST6GAL2 to promote disease progression." (PMID 31065463, 2019).
thyroid cancer (2 papers, 2021 to 2023). "Other sialyltransferases that were evaluated in thyroid cancer cell lines are members of the α-2,8-sialyltransferase (ST8SIA) family and α-2,6-sialyltransferase 2 (ST6GAL2)." (PMID 38003522, 2023).
bladder cancer (1 paper, 2023). "Among the 412 bladder cancer samples, 42 (10.19%) experienced mutation in the 8 SiaTs which were ST6GALNAC1, ST3GAL6, ST8SIA2, ST6GAL2, ST6GAL1, ST6GALNAC5, ST6GALNAC3, and ST3GAL5." (PMID 37968767, 2023).
brain tumors (1 paper, 2022). "While our study has only explored the role of α2,6 sialylation and ST6GAL1 in BTICs in vitro and in immunocompromised mouse models, we acknowledge the potential importance of ST6GAL1 and/or ST6GAL2 in the brain tumor microenvironment." (PMID 36345944, 2022). "While these pathways are known to play critical roles in brain tumors, the levels, or ability, of ST6GAL1, ST6GAL2, or α2,6 sialylation to modulate BTIC signaling or maintenance to increase glioma growth has not been investigated." (PMID 36345944, 2022).
invasive ductal carcinoma (1 paper, 2019). "ST6GAL2 upregulation may be implicated to growth and proliferation in invasive ductal carcinoma (IDC)." (PMID 30704472, 2019).
ovarian carcinoma (1 paper, 2017). A malignant neoplasm originating from the surface ovarian epithelium. "The additional profiling of other sialyltransferase genes, ST6GAL2, ST3GAL4 and ST3GAL5, was found to display varying gene expression levels between both cancer tissue types and across all tested ovarian cancer cell lines." (PMID 28853212, 2017).
prion disease (1 paper, 2022). A transmissible disease that is caused by a protein that is able to induce abnormal folding of normal cellular proteins, leading to characteristic spongiform brain changes, which are associated with neuronal loss without an inflammatory response. "Our data indirectly points to the involvement of ST6GAL2, the only other known sialyltransferase to be able to construct the α2,6-Sia linkage in PrP, in the pathogenic progression of prion disease." (PMID 36452458, 2022). "It would be interesting to test whether a knockout of ST6Gal2 or a double knockout of ST6Gal1 and ST6Gal2 affect prion disease pathogenesis." (PMID 36452458, 2022).
sporadic CJD (1 paper, 2022). "As such, testing a knockout of ST6Gal2 in future studies might provide new insight into etiology of sporadic CJD." (PMID 36452458, 2022).
cancer (12 papers, 2017 to 2024). A tumor composed of atypical neoplastic, often pleomorphic cells that invade other tissues. "The ST6GAL2 encodes a sialyl transferase that is involved in several biological processes, such as cell adhesion, signal transduction, receptor activation and cancer progression." (PMID 34575042, 2021). "In the realm of cancer, ST6GAL2 is overexpressed in certain types, including breast cancer, where its elevated expression correlates with poor patient prognosis." (PMID 39296044, 2024). "Consistently, silencing of ST6GAL2 negatively affected cancer progression by inhibiting cell adhesion and invasion, and reducing the expression of ICAM-1, VCAM-1, CD24, MMP2, MMP9, and CXCR4." (PMID 33921986, 2021). "In the ST6GAL family, ST6GAL1 is ubiquitously expressed and is the most investigated ST in cancer, while ST6GAL2 is mainly expressed in the brain." (PMID 33921986, 2021). "DNA methylation of ST6GAL2 has been proposed as a cancer biomarker for screening and detection." (PMID 30704472, 2019). "Furthermore, we have identified three genes implicated in cancer metastasis – MMP13, ST6GAL2, and ENPP1, which pazopanib has demonstrated to downregulate in our study and could act as drug-response biomarkers or a druggable target with regards to the latter." (PMID 35365682, 2022). "Overlap of upregulated genes in the tumor tissue with downregulated genes in the cell line treated with pazopanib identified three genes involved in cancer invasion and metastasis (MMP13, ST6GAL2, and ENPP1)." (PMID 35365682, 2022). "The specific role of ST6GAL2 in skeletal muscle is not fully understood, as this is a relatively new class of enzymes, and most research on the ST6GAL family of enzymes has focused on the immune system and cancer." (PMID 39296044, 2024).
tumor (11 papers, 2018 to 2024). "We further sought to examine the impact of ST6GAL2 mutations on protein expression levels in tumor tissue." (PMID 34026427, 2021). "We performed immunohistochemical (IHC) staining of ST6GAL2 in paired mutation and wild genotype pretreatment tumor biopsies from the discovery sample." (PMID 34026427, 2021). "In the ST6GAL2mut cases, lower ST6GAL2 protein expression was observed in tumor tissue and revealed resistance to NACT (p = 0.0155)." (PMID 34026427, 2021). "Correspondingly, an immunostaining analysis of xenografted tumour tissues revealed that ST6GAL2 and Ki67 expression was also increased in the FTC133/HCP5 group, whereas the inverse was found in the FTC238/si-HCP5 group." (PMID 29515098, 2018). "Notably, silencing of ST6GAL2 in follicular thyroid carcinoma has reduced tumor growth in vivo models." (PMID 39296044, 2024). "Additionally, ST6GAL2 overexpression has been shown to inhibit the Hippo signaling pathway, a tumor suppressor pathway that regulates cell differentiation and proliferation by restraining the YAP and TAZ transcriptional coactivators." (PMID 39296044, 2024). "Similarly, silencing ST6GAL2 in a follicular thyroid carcinoma reduced tumor growth by inactivating the Hippo pathway in an in vivo model." (PMID 37372117, 2023). "Findings from this study suggest that the overexpression of ST6GAL2 leads to the suppression of the Hippo signaling pathway, a tumor suppressor pathway that regulates cellular differentiation and proliferation by inhibiting YAP and TAZ transcription co-activators." (PMID 34975914, 2021). "Since these two ST6GALs have discrete carbohydrate preferences, the present results may suggest the importance of investigating potential functions of ST6GAL2 in tumor pathophysiology." (PMID 32232009, 2020). "Moreover, immunostaining demonstrated that the expression of ST6GAL2 was up-regulated in the FTC tissues with high expression of HCP5 as well as in xenograft tumour tissues in the FTC133/HCP5 group." (PMID 29515098, 2018). "Similarly, silencing of ST6GAL2 in FTC reduced tumor growth in an in vivo model." (PMID 34975914, 2021). "Of note, MMP13 was specifically expressed within the tumor and not in the normal component; ST6GAL2 and ENPP1 were highly expressed in tumor tissue compared to adjacent normal tissue (log2-foldchange 4.26 and 2.94, respectively)." (PMID 35365682, 2022). "Tumor cells highly expressed donor synthesis genes (NANS, CMAS, and the transporter SLC35A1), while the stroma showed enriched expression of sialyltransferases involved in α2-3, α2-6 and α2-8 sialylation (ST3GAL2, ST3GAL5, ST6GAL2, ST6GALNAC5, ST6GALNAC6, ST8SIA1 and ST8SIA2)." (PMID 38594506, 2024).
inflammation (1 paper, 2020). Aberrant reaction of the microcirculation characterized by movement of fluid and leukocytes from the blood into extravascular tissues. "The third and final constructed network indicated a potential prominent role for the highly overexpressed ST6GAL2 in resolution of acute airway inflammation (as this covers the comparison of asthmatic horses in exacerbation to asthmatic horses in remission)." (PMID 32998415, 2020).
ST6GAL2 also shares sentences with these, for which no sentence is quoted: cervical cancer (1 paper); cervical squamous cell carcinoma (1); Cognitive impairment (1); glioma (1); lung carcinoma (1); mucosal melanoma (1); prostate carcinoma (1); schizophrenia (1); triple-negative breast carcinoma (1).